PFN1 (profilin 1)
Diseases named in the same sentence as PFN1 in open-access papers (continued):
Sharing a sentence is not in itself a finding about the gene and the disease.
tumor (continued). "This inhibitory effect of curcumin is similar to that of profilin-1 (Prof-1), although its overexpression in cancer can reduce the tumorigenicity of the cells and inhibit cancer migration, thus indicating that Prof-1 is a tumour suppressor." (PMID 33670440, 2021). "In addition to PLP-binding, actin-binding was also suggested to be important for tumor inhibition by Pfn1." (PMID 34235154, 2021). "In addition to suppressing tumor growth, Pfn1 also sensitizes cancer cells to drug-induced apoptosis." (PMID 34235154, 2021). "PFN1 is a negative regulator of the cytotoxic cell-mediated elimination of target cells, and in vitro downregulated PFN1 promotes cytotoxic TC invasion into mimical tumor environment." (PMID 34824394, 2021). "Among the cytoskeletal-associated proteins that identified in conditioned medium of SCLC cell lines and that were elevated in both early stage and pre-clinical case plasmas were PFN1 and VCL, which have similarly been linked to promoting tumor progression and invasiveness." (PMID 34439128, 2021). "Since BC recurrence involves either metastatic or locoregional outgrowth of therapy-resistant tumour cells, we interrogated the effects of Pfn1 and Pfn2 transcript levels on the RFS and the OS of BC patients (3951 samples) using pre-assembled transcriptome datasets available from kmplot.com." (PMID 30318519, 2018). "A recent study has shown that PROF1, a component of G‐actin‐binding protein, acts as a tumour suppressor gene that adds ATP‐bound G‐actin to the barbed ends of growing cytoskeleton filaments, correlating Pfn1 expression with motility and invasiveness of tumour cells." (PMID 27709782, 2017). "Therefore, the increase in PFN1 expression induced by GUTK treatment highly coincides with a reduction in the expression of tumor metastasis markers." (PMID 27494863, 2016). "As in some cases, PFN1 has been suggested to impact on angiogenesis, we investigated whether the observed decrease in tumor growth or metastasis correlates with a decrease in angiogenesis following PFN1 suppression." (PMID 27683119, 2016). "Tumor migration may be further suppressed by increased secretion of known tumor suppressor factors following PFN1 suppression." (PMID 27683119, 2016). "We next examined the in vivo effects of Pfn1 expression on tumor growth." (PMID 25103363, 2014). "Deregulation of PFN1 has been reported in various adenocarcinomas (breast, pancreas, hepatic, and gastric), and indicating that the molecule may function as a tumor-suppressor gene." (PMID 24587265, 2014). "Overexpression of Pfn1 in vivo decreased the tumor volume in orthotopic xenograft nude mice models." (PMID 25103363, 2014). "Conversely, downregulation of Pfn1 in SW1990 cells promoted tumor growth subcutaneously." (PMID 25103363, 2014). "Our results demonstrate that increased adhesion, migration and invasiveness of tumor cells depend on the inactivation of the tumor suppressive function of profilin 1 by cathepsin X. The latter is thus designated as a target for development of new antitumor strategies." (PMID 23326535, 2013). "Since profilin 1 acts as a tumor suppressor, the impairment of its function may lead to increased motility and invasion of tumor cells, as shown in this and other studies." (PMID 23326535, 2013). "Future studies are needed to determine whether targeted overexpression of Pfn1 in preformed tumours slows down distant metastasis." (PMID 17940506, 2007). "A study showed consistently lower profilin 1 levels in tumor cells." (PMID 15784140, 2005). "While PFN1 overexpression may suppress tumor growth in certain settings by promoting the accumulation of the cell cycle inhibitor p27, it can also enhance actin polymerization and cytoskeletal remodeling, processes that facilitate cell motility and invasiveness." (PMID 40981267, 2025). "Furthermore, the downregulation of profilin-1 (Pfn1), a protein involved in actin polymerization, may contribute to tumor progression." (PMID 40710368, 2025).
tumor (continued). "In addition, Pfn1 expression was inversely correlated with tumor differentiation." (PMID 25103363, 2014). "Of these 21, we focused on 5 proteins (YWHAE, PFN1, LCP1, IGHM, CD5L) that were enriched in external CNSL cohorts, thereby supporting their utility as CNSL-enriched tumor burden biomarkers." (PMID 40321620, 2025). "Profilin 1 (PFN1) is a member of the actin-binding protein family and has a tissue context-specific role in cell migration and tumor malignancy." (PMID 38684875, 2024). "On the other hand, overexpression of PFN1 in cells with high levels of SH3BGRL can counteract SH3BGRL-induced metastasis and tumor growth by upregulating PTEN and inhibiting the PI3K-AKT pathway." (PMID 38609844, 2024). "The study collected tumor and adjacent normal lung tissue samples from 46 NSCLC patients and used real-time PCR and Western blotting to determine the levels of PFN1, FSCN1, and EZR mRNAs and proteins." (PMID 38609844, 2024). "This is consistent with the poor performance of PFN1 to classify latent DFTD, considering tumor volume is presumably at a minimum at the preclinical disease stage." (PMID 35422813, 2022). "Many studies on the role of the actin cytoskeleton in tumor progression have focused on ABPs, specifically cofilin-1 (CFL1) and profilin-1 (PFN1)." (PMID 37226274, 2022). "To further investigate the role of PFN1 in NSCLC metastasis, we established a mouse model of tumor metastasis via intracardiac injection of H1299 NSCLC cells." (PMID 35586060, 2022). "In this study, we systematically explored the roles of PFN1 in tumor metastasis and MV secretion in NSCLC, and confirmed that PFN1 promoted NSCLC metastasis by promoting the secretion of MVs in vitro and in vivo." (PMID 35586060, 2022). "Generally, HLA-F-AS1 is upregulated in cancers and affects the expression of cancer-related genes, such as PFN1 and TRABD, to promote tumor metastasis and growth." (PMID 35603775, 2022). "Thus, by identifying and characterizing a previously unknown inhibitory phosphorylation event for actin-binding of Pfn1, we provided further mechanistic insights into its multifaceted tumor-inhibitory activities which are regulated both by ligand-binding and subcellular localization." (PMID 34235154, 2021). "We also identified YWHAE, PFN1, LCP1, IGHM, and CD5L as potential tumor burden markers." (PMID 40321620, 2025). "While the potential tumor burden markers (YWHAE, PFN1, LCP1, IGHM, CD5L) are relatively abundant in CSF and have been previously implicated in various malignancies beyond CNSL, our study uniquely demonstrates their value in monitoring CNSL disease progression and treatment response." (PMID 40321620, 2025). "Homozygous Pfn1 knock-in mice are not viable, while, curiously, heterozygous mice grow normally and display no overt tumour phenotype." (PMID 36599901, 2023). "CATH3 and PFN1 did not demonstrate a significant positive correlation with tumor volume but showed a binary relationship with disease/healthy demonstrated in the discovery and validation cohorts." (PMID 35422813, 2022). "Despite being an essential actin-binding protein, Pfn1 simultaneously functions as a non-classical tumor suppressor across different malignancies including breast, pancreatic, and liver cancers." (PMID 34235154, 2021). "The essential actin-binding factor profilin-1 (Pfn1) is a non-classical tumor suppressor with the abilities toboth inhibit cellular proliferation and augment chemotherapy-induced apoptosis." (PMID 34235154, 2021). "Immunohistochemical analysis at T24MshPFN1 tumor sections confirmed the absence of PFN1 protein expression even 60 days after the cell injection." (PMID 27683119, 2016). "We confirmed these results via Western blotting analysis of tumor cells expressing AFAP1-AS1 siRNA, and found that RhoA, Rac2, Rab10, Rab11a, Rhogdi and Pfn1 were significantly upregulated, but RhoC, Rab11b and Lasp1 were significantly downregulated in NPC cell lines." (PMID 26246469, 2015).
tumor (continued). "This knowledge gap is partly due to lack of reports correlating Pfn1 expression with motility and invasiveness of tumour cells and/or their normal counterparts." (PMID 17940506, 2007). "Notably, tumor xenografts derived from PFN1-silenced cells in mice formed significantly smaller, non-metastatic tumors." (PMID 40981267, 2025). "Based on the analysis of the number of subpopulations expressing CFL1, PFN1 and CAP1, the characteristics of CTCs pools and peripheral blood leukocyte pools in patients with HNSCC were given in relation to the main clinical and pathological characteristics of the tumor." (PMID 37226274, 2022). "Thus, unlike the toggling effect of Ser137 phosphorylation, tumor inhibition by Pfn1 appears to require reversible Ser71 phosphorylation and dephosphorylation." (PMID 34235154, 2021). "Whether overexpression of Pfn1-elicits similar tumour-suppressive effect at the orthotopic site is not known." (PMID 17940506, 2007). "Unlike CATH3, PFN1 was detected in the cell culture DFTD EV database, suggesting a possible tumor origin." (PMID 35422813, 2022). "Finally, even though our in vivo studies show lack of micro-metastasis of Pfn1-expressing cells, we cannot resolve whether this is due to failure of these cells to disseminate via reduced migration and invasion (as suggested by in vitro studies) or lack of tumour formation." (PMID 17940506, 2007).
cancer (42 papers, 2007 to 2026). A tumor composed of atypical neoplastic, often pleomorphic cells that invade other tissues. "However, the role of PFN1 differs from cancer to cancer, and the mechanisms underlying PFN1 function in cancer metastasis are not fully understood." (PMID 35586060, 2022). "Numerous studies revealed that PFN1 plays a vital role in membrane trafficking, thus providing insights into the mechanism underlying its function in cancer metastasis." (PMID 35586060, 2022). "Finally, several disease-variants of PFN1 have been identified in cancer and neurodegenerative disorders." (PMID 35666129, 2022). "Therefore, the effects and corresponding underlying mechanisms of profilin 1 demonstrated a cancer-dependent manner, which needed to be explored in MPNST." (PMID 33163494, 2020). "Pfn1 expression levels were strongly associated with cancer-specific survival." (PMID 25103363, 2014). "These interesting observations appear to suggest that loss of Pfn1 expression may have a general relevance in cancer progression." (PMID 17940506, 2007). "There are four isoforms of profilin identified so far, of which profilin-1 is the most highly regarded due to its role in the cytoskeleton and in cell signaling and its link to cancer and vascular hypertrophy." (PMID 41573035, 2025). "Apart from these markers, Plectin (PLEC) and Profilin 1 (PFN1) that are previously reported as metastasis regulators in different cancers, showed differential expression in our study." (PMID 37770851, 2023). "In cancer cells, overexpression of PFN1 has been shown to impact PTEN levels, preventing its degradation by the proteasome." (PMID 35628504, 2022). "As PFN1 is important in membrane trafficking and MVs are key mediators of cancer metastasis, we extracted extracellular vesicles (MVs and exosomes) from sera of clinical samples." (PMID 35586060, 2022). "Previous studies pertaining to the role of PFN1 in cancer metastasis have yielded contrasting results, PFN1 exhibits variable effects on the metastasis of different tumors." (PMID 35586060, 2022). "The role of profilin 1 in cancer development and progression has been investigated while heterogeneity still exists." (PMID 33163494, 2020). "A reduction in PFN1 protein levels has been reported in cancers of the breast, esophagus, pancreas, larynges, and bladder." (PMID 27494863, 2016). "Quantification of the IHC intensity revealed a reduction of PFN1 expression as cancer stage progresses." (PMID 27683119, 2016). "As such, to monitor PFN1 expression throughout cancer invasion and progression, we generated NOD/SCID xenografts, utilizing the T24M metastatic cell line." (PMID 27683119, 2016). "Remarkably, FRAP analysis of PFN1 overexpressing cancer cells also revealed impaired actin dynamics characterized by an elevated percentage of stable F-actin." (PMID 25629407, 2015). "To test this possibility, we first investigated the possibility that Pfn1 interacts with SIRT3 in cancer cells." (PMID 25103363, 2014). "Densitometric analysis of the western blots revealed profilin 1 was 3.6±2.5-fold (*p<0.01) elevated in cancer tissues." (PMID 25084196, 2014). "The effect of Pfn1 expression on cancer proliferation was assessed in cells by up- and down-regulation of Pfn1 in vitro and in vivo." (PMID 25103363, 2014). "Various cell lines from different cancers behaved differently with overexpression or abrogation of profilin 1 with respect to cell migration, invasion and proliferation." (PMID 25084196, 2014). "Patients with high Pfn1 expression had significant better cancer-specific survival than patients with low Pfn1 expression." (PMID 25103363, 2014). "A spot corresponding to around 16 kDa, with intensity 1 in non-treated cells and intensity 3.4 (arrow) in treated cells, was identified as human profilin 1, a protein known to influence the motility of invasive cancer cells." (PMID 23326535, 2013).
cancer (continued). "Moreover, the development of in vivo models with tissue-specific PFN1 deletions will be instrumental in determining its role in morphogenesis and cancer metastasis." (PMID 40981267, 2025). "Finally, a notable correlate to our finding that NEDD4 inhibits PFN1 function in NCCs are the contrasting roles of these proteins in cancer and neurodegeneration." (PMID 35440627, 2022). "Nevertheless, our data strongly suggested that increasing nuclear PFN1 by inhibiting XPO6 could be a promising therapeutic approach to sensitize cancer cells, which frequently overexpress XPO640, to replication stress-inducing chemotherapies." (PMID 36319634, 2022). "Pfn1 overexpression inhibits the growth of various cancer cell lines in vitro and in vivo." (PMID 34235154, 2021). "In addition to suppressing proliferation, Pfn1 also sensitizes cancer cells to apoptosis induced by cytotoxic agents." (PMID 34235154, 2021). "Furthermore, we provided evidence that Pfn1 undergoes spatial deregulation in a broad range of cancer due to overexpression of its nuclear exporter exportin-6." (PMID 34235154, 2021). "Whether elevated profilin 1 levels alone are indicative of increased motility and aggressive cancers is debatable." (PMID 25084196, 2014). "Since Pfn1 has been traditionally viewed as a molecular player required for cell migration, it is not at all clear why Pfn1 expression is downregulated in various forms of invasive cancer cells." (PMID 17940506, 2007). "Inhibitors targeting profilin 1 phosphorylation directly or indirectly through inhibition of kinases that phosphorylate profilin could be valuable therapeutic agents that can alter its activity and thereby control the progression of cancer." (PMID 25084196, 2014). "To evaluate the relevance of the reduced PFN1 to human HCC, we examined PFN1 expression in 86 individual HCCs and their adjacent non-cancer tissue specimens by immunohistochemical analysis." (PMID 27494863, 2016). "This PFN1 expression pattern is in agreement with our previous observations in human tissue specimens, when comparing non-invasive (T1G3) and invasive T2+ cancer." (PMID 27683119, 2016). "Pfn1-FLAG and SIRT3-HA fusion constructs were transiently introduced into the cancer cell line MIA PaCa-2." (PMID 25103363, 2014). "In most cases, PFN1, NCL and CNDP2 exerted an increased mRNA expression, while OGN displayed a decreased level in the carcinoma tissues compared with the adjacent normal tissue." (PMID 24587265, 2014). "Finally, given PFN1’s contrasting roles in distinct cancer types, exploring its potential as a context-dependent therapeutic target could pave the way for more personalized treatment strategies, particularly in muscle-invasive cancers where Wnt/Ca2+ signaling is disrupted." (PMID 40981267, 2025). "Profilin 1 (PFN1), an actin-binding protein, plays contrasting roles in the metastasis of several cancers; however, its role in non-small cell lung cancer (NSCLC) metastasis remains unclear." (PMID 35586060, 2022). "The interactions between PFN1 and ROCK1 may be much more complex in vivo and play important roles in cancer progression, which needs further investigation in the future." (PMID 35586060, 2022). "Our more recent work supported this theory and demonstrated that nuclear Pfn1 functions as a transcriptional repressor by binding and inhibiting the Super Elongation Complex (SEC), a positive regulator of transcriptional elongation of many pro-cancer genes." (PMID 34235154, 2021). "Seven out of 52 genes (GSTP1, HSP90B1, HSPB1, PFN1, RAP1A, SFN, YWHAZ) were assigned to KEGG pathways in cancer, cell migration and cell cycle, and in signaling networks involved in proliferation, cellular motility, apoptosis, cell adhesion, angiogenesis and genetic integrity." (PMID 30157864, 2018).
cancer (continued). "Importantly, target genes involved in epithelium development (RGMA, SHANK3, PAX6, PFN1, WNT4) and cancer (CBL, CYCS, FGF7, IGF1R, PTEN, PIK3CD, WNT4) address to a further role in the onset of epithelial abnormalities and oncogenesis." (PMID 23936163, 2013). "We noted significant reductions in the PFN1 protein levels (comparing negative staining against 1+, 2+ and 3+ combined) or the percentage of PFN1 positive cells in later stage (T3 and T4) HCC, compared to their own adjacent non-cancer tissues." (PMID 27494863, 2016). "Reduction of PFN-1 expression by elevated PrPc levels might prove important not only as so far unrecognized contributing factor for increased resistance of PrPc-overexpressing SH-SY5Y cells to STS-induced apoptosis, but also in the light of emerging roles of these two proteins in cancer." (PMID 28102851, 2017).
neurodegenerative disease (7 papers, 2022 to 2025). A disorder of the central nervous system characterized by gradual and progressive loss of neural tissue and neurologic function. "Our study suggests that disruption of RNA metabolism could be a potential pathological mechanism underlying neurodegenerative diseases associated with PFN1." (PMID 40409555, 2025). "Moreover, the cytoskeletal modifications resulting from PFN1 depletion in neuronal processes affected microtubule-based transport and mimicked phenotypes that are linked to neurodegenerative disease." (PMID 38722279, 2024). "We identified several genes associated with neurodegenerative diseases, including PFN1 and INPP5D, as modulators of phagocytosis in microglia, thus pointing to a possible cellular mechanism by which variants in these genes contribute to disease (Supplementary Discussion)." (PMID 35953545, 2022). "This not only expands the biological role of PFN1 but also identifies it as a critical factor in neurodegenerative diseases, like ALS, which are characterized by the dysregulation of MLOs." (PMID 40409555, 2025). "As mutations in the Profilin-1 gene have potential implications in neurodegenerative disease progression, well-characterized anti-Profilin-1 antibodies would be beneficial to the scientific community." (PMID 37576538, 2023).